ST20 (suppressor of tumorigenicity 20)
Description:
May act as a tumor suppressor. Promotes apoptosis of cancer cells.
Synonyms: HCCS-1
Gene: Long non-coding RNA gene on chromosome 15 (79,898,840 to 79,923,702, reverse strand). Ensembl gene ENSG00000180953.
Genetic constraint (gnomAD): Loss-of-function variants: 2 observed, 3.52 expected, observed/expected ratio (o/e) 0.57, 90% interval 0.23 to 1.62. That is too few expected variants to judge how well the gene tolerates losing a copy. Missense variants: 33 observed, 50 expected, observed/expected ratio (o/e) 0.66, 90% interval 0.5 to 0.88. Synonymous variants: 12 observed, 15.07 expected, observed/expected ratio (o/e) 0.8, 90% interval 0.51 to 1.29.
Diseases named in the same sentence as ST20 in open-access papers:
ST20 is named in the same sentence as 5 diseases in open-access papers, as found by Europe PMC text mining. Sharing a sentence is not in itself a finding about the gene and the disease. The quoted sentences say what the papers report.
cervical cancer (1 paper, 2024). A primary or metastatic malignant neoplasm involving the cervix. "ST20, also known as HCCS-1, exhibits downregulated expression in a variety of human malignancies, potentially fulfilling the role of a tumor suppressor gene by activating apoptotic signaling pathways, thereby restraining the progression of cervical cancer." (PMID 39309810, 2024).
ischemia (1 paper, 2017). A hypoperfusion of the BLOOD through an organ or tissue caused by a PATHOLOGIC CONSTRICTION or obstruction of its BLOOD VESSELS, or an absence of BLOOD CIRCULATION. "Small alterations in ST20 in boundary LV area of H group data were negligible in comparison with ischemia-induced ST deviation observed in both groups (at least 2 mV at the middle of ischemia)." (PMID 28778146, 2017).
infection (1 paper, 2021). The state of being infected such as from the introduction of a foreign agent such as serum, vaccine, antigenic substance or organism. "ST20 isolates also caused cytokine induction with CM-SC1 resulting in induction of 8/10 cytokines and 3/6 cytokines, and HA-WI2 infection inducing 5/10 cytokines but 0/6 chemokines." (PMID 34516359, 2021).
ST20 also shares sentences with these, for which no sentence is quoted: endothelial dysfunction (1 paper); tumor (1).